ENSG00000267120 (novel transcript)
Gene: Protein-coding gene on chromosome 19 (35,739,252 to 35,745,432, reverse strand). Ensembl gene ENSG00000267120.
Genetic constraint (gnomAD): Missense variants: 130 observed, 127.53 expected, observed/expected ratio (o/e) 1.02, 90% interval 0.88 to 1.18. Synonymous variants: 45 observed, 45.4 expected, observed/expected ratio (o/e) 0.99, 90% interval 0.78 to 1.27.